ZNF2 (zinc finger protein 2)
Description:
May be involved in transcriptional regulation.
Synonyms: ZNF661; A1-5; Zfp661
Tractability: Antibody: the Human Protein Atlas places it where antibodies can reach. PROTAC: ubiquitination databases record sites on it.
Gene: Protein-coding gene on chromosome 2 (95,165,432 to 95,184,317, forward strand). Ensembl gene ENSG00000275111.
Subcellular location: Nucleus
Subcellular location (Human Protein Atlas): Cytosol; Plasma membrane; Nucleoplasm
Pathways (Reactome):
Gene expression (Transcription): Generic Transcription Pathway
Gene Ontology:
Molecular function: protein binding; zinc ion binding
Biological process: regulation of DNA-templated transcription
Cellular component: nucleus
Genetic constraint (gnomAD): Loss-of-function variants: 15 observed, 24.75 expected, observed/expected ratio (o/e) 0.61, 90% interval 0.41 to 0.93. The upper end of that interval is the gene's LOEUF score, 0.93, which puts it in group 3 of 6, group 1 being the genes least tolerant of losing a copy. Missense variants: 452 observed, 562.15 expected, observed/expected ratio (o/e) 0.8, 90% interval 0.74 to 0.87. Synonymous variants: 183 observed, 203.75 expected, observed/expected ratio (o/e) 0.9, 90% interval 0.8 to 1.01.
Homologues: Orthologues: chimpanzee ZNF2 (99% identical), macaque ZNF2 (95% identical), dog ZNF2 (84% identical), rabbit ZNF2 (82% identical), guinea pig ZNF2 (82% identical), pig ZNF2 (81% identical), mouse Zfp661 (80% identical), rat LOC100909998 (76% identical). Paralogues in human: ZNF568 (43% identical), ZNF7 (43% identical), ZNF658 (43% identical), ZNF879 (43% identical), ZNF585B (43% identical), ZFP28 (42% identical), ZNF250 (42% identical), ZNF33B (42% identical), ZNF471 (42% identical), ZNF484 (42% identical), ZNF189 (42% identical), ZNF300 (41% identical), and 164 more.
Diseases named in the same sentence as ZNF2 in open-access papers:
ZNF2 is named in the same sentence as 8 diseases in open-access papers, as found by Europe PMC text mining. Sharing a sentence is not in itself a finding about the gene and the disease. The quoted sentences say what the papers report.
cryptococcosis (4 papers, 2010 to 2015). An acute or chronic, localized or disseminated infection by Cryptococcus neoformans. "We further examined the fungal burden in the lungs and the brain of animals infected with H99, the znf2Δ mutant, and the PGPD1-ZNF2 strain at DPI 10 before any animal succumbed to cryptococcosis." (PMID 22737071, 2012). "Besides its anti-virulence effect during cryptococcal infection in a mammalian host, Znf2 also shapes cryptococcal interaction with other heterologous hosts, such as the soil amoeba Acanthamoeba castellanii and the insect Galleria mellonella." (PMID 26588844, 2015). "Znf2 is an anti-virulence factor in the mouse model of cryptococcosis." (PMID 26588844, 2015). "Importantly, ZNF2 overexpression abolishes fungal virulence in murine models of cryptococcosis." (PMID 22737071, 2012). "Thus manipulation of ZNF2 activity could be a potential means to alleviate cryptococcosis." (PMID 26588844, 2015). "Unlike Znf2, overexpression of CFL1 attenuates but does not abolish Cryptococcus virulence in the murine model of cryptococcosis." (PMID 22737071, 2012).
breast carcinoma (1 paper, 2014). "Interestingly, while HDR GATA3 mutations are spread throughout the gene, breast cancer mutations cluster around ZnF2 and C-terminal domain." (PMID 24758297, 2014). "We utilized two luminal breast cancer cell lines, MCF7 harboring a heterozygous frameshift mutation in ZnF2, and T47D carrying wild-type version GATA3." (PMID 24758297, 2014).
diabetes mellitus (1 paper, 2022). A metabolic disorder characterized by abnormally high blood sugar levels due to diminished production of insulin or insulin resistance/desensitization. "Certainly, it is worth to broaden the study and analyze the contribution of Zinc Finger Protein 2 in the pathophysiology of diabetes mellitus." (PMID 35327145, 2022). "There is lack of information regarding Zinc Finger Protein 2 in diabetes mellitus." (PMID 35327145, 2022).
infection (2 papers, 2012 to 2016). The state of being infected such as from the introduction of a foreign agent such as serum, vaccine, antigenic substance or organism. "High expression of Znf2 is necessary and sufficient to initiate and maintain sex-independent filamentous growth under host-relevant conditions in vitro and during infection." (PMID 22737071, 2012). "Finally, we analyzed a less frequent but equally interesting set of genes linked by one motif: the FoxP coiled coil domain, found in three proteins of C. neoformans (Znf2, Zap103, and Rim101), all of which decrease virulence in a mouse model of infection." (PMID 27833589, 2016).
ZNF2 also shares sentences with these, for which no sentence is quoted: hepatocellular carcinoma (2 papers); cancer (1); liver cancer (1); tumor (1).